DSTN (destrin, actin depolymerizing factor)
Description:
Actin-depolymerizing protein. Severs actin filaments (F-actin) and binds to actin monomers (G-actin). Acts in a pH-independent manner.
Synonyms: ADF; ACTDP; HEL32; bA462D18.2
Tractability: Antibody: the Human Protein Atlas places it where antibodies can reach. PROTAC: UniProt records ubiquitination sites on it; ubiquitination databases record sites on it; its protein half-life has been measured.
Gene: Protein-coding gene on chromosome 20 (17,569,152 to 17,609,919, forward strand). Ensembl gene ENSG00000125868.
Subcellular location (Human Protein Atlas): Plasma membrane
Gene Ontology:
Molecular function: actin filament binding; protein binding; actin binding; actin filament severing activity
Biological process: actin filament depolymerization; actin filament fragmentation; actin filament severing; actin polymerization or depolymerization
Cellular component: extracellular exosome; actin cytoskeleton; cytoplasm; cortical actin cytoskeleton; glutamatergic synapse; postsynapse; presynapse
Genetic constraint (gnomAD): Loss-of-function variants: 10 observed, 16.88 expected, observed/expected ratio (o/e) 0.59, 90% interval 0.36 to 1. The upper end of that interval is the gene's LOEUF score, 1, which puts it in group 4 of 6, group 1 being the genes least tolerant of losing a copy. Missense variants: 141 observed, 202.54 expected, observed/expected ratio (o/e) 0.7, 90% interval 0.61 to 0.8. Synonymous variants: 57 observed, 61.39 expected, observed/expected ratio (o/e) 0.93, 90% interval 0.75 to 1.16.
Homologues: Orthologues: chimpanzee DSTN (100% identical), dog DSTN (100% identical), macaque DSTN (100% identical), guinea pig DSTN (99% identical), pig DSTN (98% identical), mouse Dstn (96% identical), rat Dstn (96% identical), Drosophila melanogaster tsr (29% identical), Caenorhabditis elegans F53E2.2 (25% identical), Drosophila melanogaster CG6873 (25% identical), Caenorhabditis elegans unc-60 (25% identical). Paralogues in human: CFL1 (72% identical), CFL2 (69% identical).
Diseases named in the same sentence as DSTN in open-access papers:
DSTN is named in the same sentence as 22 diseases in open-access papers, as found by Europe PMC text mining. Sharing a sentence is not in itself a finding about the gene and the disease. The quoted sentences say what the papers report.
lung carcinoma (3 papers, 2024 to 2025). "Using this approach, we uncovered a regulatory region upstream of DSTN in the lung carcinoma cell line." (PMID 39660643, 2025). "DSTN, a key factor regulating cytoskeletal reorganization, affects the migration and invasive ability of lung cancer cells by promoting β‐catenin nuclear translocation‐mediated EMT." (PMID 39098994, 2024).
prostate carcinoma (2 papers, 2017 to 2025). A carcinoma that arises from epithelial cells of the prostate gland. "Among these genes, high expression of certain genes, such as FLNA and DSTN, is positively correlated with the prognosis of prostate cancer patients, while elevated expression of other genes, including FLNB and INF2, is associated with a negative prognosis." (PMID 41049007, 2025). "The percentages of alterations in these genes among prostate cancer varied from 13-30% for individual genes (CAP2, 19%; CAP1, 13%; CFL1, 30%; CFL2, 21%; DSTN, 19%); the CFL1 gene was amplified predominantly in the prostate cancer type." (PMID 28423713, 2017). "For example, percentages of alterations in CAP2, CAP1, CFL1, CFL2, DSTN, ACTB, and ACTG1 genes among prostate cancer varied from 2.6–30% in individual genes (CAP2, 19%; CAP1, 13%; CFL1, 30%; CFL2, 21%; DSTN, 19%; ACTG1, 2.6%; ACTB, 21%;); the CFL1 gene was amplified predominantly in prostate cancer." (PMID 28423713, 2017).
acute coronary syndrome (1 paper, 2024). Signs and symptoms related to acute ischemia of the myocardium secondary to coronary artery disease. "Compared with the acute coronary syndrome (ACS), CD2AP and DSTN were higher expressed in monocytes cell of stable angina pectoris (SAP), and RPN1 was higher expressed in B cell of SAP." (PMID 39666769, 2024).
bladder cancer (1 paper, 2024). "Most disulfidoptosis genes were downregulated in multiple cancer types, including PDLIM1, TLN1, and MYH10 in lung squamous cell carcinoma (LUSC), MYL6 and DSTN in prostate adenocarcinoma (PRAD), and FLNA and ACTB in bladder cancer (BLCA)." (PMID 38862242, 2024).
bladder urothelial carcinoma (1 paper, 2024). "Single-cell analysis revealed that ACTB, DSTN, and MYL6 were highly expressed in different bladder urothelial carcinoma subtypes, but MYH10 showed a low expression." (PMID 38584831, 2024).
head and neck squamous cell carcinoma (1 paper, 2024). A squamous cell carcinoma that arises from any of the following anatomic sites: lip and oral cavity, nasal cavity, paranasal sinuses, pharynx, larynx, and salivary glands. "In our study, DSTN was found to be significantly associated with tumor progression and showed higher expression levels in head and neck squamous cell carcinoma (HNSCC)." (PMID 39896807, 2024).
head-neck cancer (1 paper, 2017). "The co-expression analysis revealed that CAP1 was coexpressed with TUBA1B in pancreatic and head-neck cancer, as well as with CFL1, CFL2, DSTN, ACTB, ACTG1, and ROBO1, according to the STRING analysis." (PMID 28423713, 2017). "Co-expression analysis revealed that CAP1 was coexpressed with TUBA1B both in pancreatic and head-neck cancer, as well as with CFL1, CFL2, DSTN, and ROBO1, according to STRING analysis." (PMID 28423713, 2017).
liver cancer (1 paper, 2017). An epithelial or non-epithelial malignant neoplasm that arises from the liver. "CAP2 was coexpressed with TP53BP2, ENA/VASP in the liver cancer, and CFL1, CFL2, DSTN, ACTB, ACTG1, and ROBO1." (PMID 28423713, 2017).
lung adenocarcinoma (1 paper, 2025). A carcinoma that arises from the lung and is characterized by the presence of malignant glandular epithelial cells. "This locus contains the fine-mapped SNP rs611572 from the UK Biobank population eQTL analysis in a matched cell type and DSTN has been noted to promote malignancy in lung adenocarcinoma." (PMID 39660643, 2025).
pancreatic cancer (1 paper, 2024). "High expression of DSTN is also associated with pancreatic cancer growth and perineural invasion." (PMID 38649690, 2024).
tumor (11 papers, 2023 to 2025). "High DSTN expression is closely associated with tumor cell proliferation." (PMID 39896807, 2024). "Specifically, an elevation in the expression levels of PRN1, OXSM, SLC3A2, and CD2AP were observed in tumor tissues, while the expression levels of DSTN, FLNA, TLN1, IQGAP1, MYL6, NCKAP1, and NDUFS1 declined in tumor tissues." (PMID 39995998, 2025). "DSTN is closely linked to EMT, a key process through which tumor cells acquire the ability to migrate and invade." (PMID 39896807, 2024). "Cellular experiments showed that DSTN was highly expressed in multiple cell lines, and clinical tissue samples revealed significantly higher DSTN expression in tumor tissues compared to normal tissues and other candidate genes." (PMID 39896807, 2024). "DSTN upregulation promotes tumor growth, and its knockout inhibits proliferation, migration, and invasion." (PMID 39896807, 2024). "DSTN’s expression is modulated by factors in the tumor microenvironment, impacting tumor progression and invasion." (PMID 39896807, 2024). "As a protein involved in cytoskeletal remodeling, DSTN has been confirmed in several studies to play a critical role in tumor cell migration, proliferation, and invasion, particularly during tumor metastasis." (PMID 39896807, 2024). "Immune infiltration analysis and transcriptomic data also indicated that DSTN is closely related to immune cell infiltration in the tumor microenvironment and tumor progression, reinforcing its reliability as a potential oncogene." (PMID 39896807, 2024). "We also found that DSTN exhibited stronger associations with pathways such as hsa-miR-181c-5p/LUCAT1, IGFL2-AS1, and hsa-miR-23b-5p, suggesting its significant role in tumor regulation." (PMID 39896807, 2024). "DSTN interacts with the cytoskeleton to promote the EMT process in tumor cells, enhancing their migratory capacity, and drives this process by regulating markers such as N-cadherin and Vimentin." (PMID 39896807, 2024). "Studies have shown that DSTN regulates cell cycle-related proteins to promote cell cycle progression and drive tumor cell proliferation." (PMID 39896807, 2024). "Furthermore, DSTN influences tumor microenvironment remodeling by interacting with cancer-associated fibroblasts (CAFs), further promoting tumor invasion and metastasis." (PMID 39896807, 2024). "Additionally, the disulfidptosis gene DSTN has been experimentally proven to be a key gene in promoting HNSCC progression by enhancing tumor cell proliferation, migration, and invasion." (PMID 39896807, 2024). "DSTN not only plays a role in actin remodeling but may also regulate tumor cell migration and invasion by activating key signaling pathways such as the Rho family GTPases." (PMID 39896807, 2024). "Additionally, DSTN was significantly overexpressed in tumor cells; its knockdown inhibited tumor cell proliferation, migration, and invasion." (PMID 39896807, 2024). "Moreover, using the TIMER database, we found that the expression of NUBPL and ACTB was closely related to tumor purity, while the correlation of SLC3A2 and DSTN with tumor purity was less pronounced." (PMID 39896807, 2024). "The presence of immune cells, fibroblasts, and other non-tumor components may modulate DSTN expression." (PMID 39896807, 2024). "In GC, ZNF331 can also curb tumor cell invasion by downregulating DSTN and ACTR3." (PMID 37174714, 2023). "Further survival analysis revealed that DSTN was significantly correlated with overall survival (OS), progression-free survival (PFS), and disease-specific survival (DSS), with P-values of 0.02, 0.015, and 0.02, respectively, further supporting its close association with tumor prognosis." (PMID 39896807, 2024). "Additionally, DSTN enhances tumor cell proliferation by modulating the β-catenin pathway." (PMID 39896807, 2024). "Of particular interest, the interactions of signaling pairs TNFSF12-TNFRSF12A mediated the interaction of both DSTN+CD4T-C1 and FLNA+CD4T-C2 subgroups with tumor epithelial cells." (PMID 38292868, 2024).
tumor (continued). "Our investigation revealed that that DSTN+CD4T and FLNA+CD4T cells interact with tumor cells through the TNF-TNFRSF1A signaling pair, thereby facilitating tumor migration." (PMID 38292868, 2024). "Results showed that ACTB, DSTN, FLNA, IQGAP1, MYL6, and TLN1 were overexpressed in normal tissues, while CD2AP and INF2 were overexpressed in tumor tissues." (PMID 37325625, 2023). "As a tumor suppressor, ZNF331 inhibits GC progression by downregulating genes that promote cell growth, such as DDX5, DSTN, EIF5A, GARS, UQCRFS1, STAM and SET." (PMID 37174714, 2023). "Since DSTN is related to cytoskeletal dynamics, it may influence the movement and efficacy of CD8 T cells in the tumor microenvironment." (PMID 40438679, 2025). "Consequently, significant score differences between tumor and normal samples were observed within two disulfidptosis-related CD4+ T cell subgroups, namely, DSTN+CD4T-C1 and FLNA+CD4T-C2." (PMID 38292868, 2024). "Consequently, DSTN could play a crucial role in tumor cell migration, invasion, and interactions with other cell types, with its expression pattern potentially having a weaker relationship with tumor purity due to dynamic regulation by the tumor microenvironment." (PMID 39896807, 2024). "Additionally, we explored the regulatory axis of DSTN/hsa-miR-181c-5p/LUCAT1 and IGFL2-AS1 in HNSCC, which may be involved in tumor invasion and metastasis." (PMID 39896807, 2024). "In contrast, DSTN, an actin-related protein involved in cytoskeletal remodeling and cell migration, may be influenced by multiple factors in the tumor microenvironment, not just by the proportion of tumor cells." (PMID 39896807, 2024). "Moreover, CellChat analysis unveiled diverse and extensive interactions between disulfidptosis-mediated TME subgroups and tumor epithelial cells, highlighting the TNFSF12-TNFRSF12A ligand-receptor pair as mediators between DSTN+CD4T-C1, FLNA+CD4T-C2, and epithelial cells." (PMID 38292868, 2024). "Recent studies have shown that overexpressed DSTN can upregulate the activity of Wnt/β-catenin signaling pathway by promoting the nuclear translocation of β-catenin and the interaction between β-catenin and TCF4, thereby promoting tumor proliferation and metastasis." (PMID 38649690, 2024). "Additionally, mRNA levels of ACTB, DSTN, FLNA, and TLN1 increased gradually with the tumor stage." (PMID 37325625, 2023). "Therefore, DSTN expression might not entirely depend on changes in tumor purity, especially in tumor samples with multiple cell populations." (PMID 39896807, 2024). "While CCL5, CD52, DSTN and IL7R still exhibited a trend of high expression in tumour samples, but no significant discrepancy existed." (PMID 39098994, 2024).
cancer (7 papers, 2017 to 2025). A tumor composed of atypical neoplastic, often pleomorphic cells that invade other tissues. "DSTN is suggested to enhance cancer cell migration and invasion by modulating actin dynamics." (PMID 40936684, 2025). "Its contribution was further reinforced by suppression interactions involving DSTN and IFITM3, highlighting its functional embedding within cancer-specific metabolic networks." (PMID 40941703, 2025). "DSTN and FLNB were downregulated when ACTIN4, INF2, MHY10, FLNA, PDLIM1, and IQGAP1 were upregulated in THCA cancer tissues." (PMID 38584831, 2024). "The cBioPortal analysis program identified 12 types of human cancer with significant CNAs in the chosen genes’ signature (CAP1, CAP2, CFL1, CFL2, DSTN)." (PMID 28423713, 2017).
DSTN also shares sentences with these, for which no sentence is quoted: Blindness (1 paper); breast carcinoma (1); carotid atherosclerosis (1); cervical cancer (1); colorectal cancer (1); esophageal cancer (1); esophageal squamous cell carcinoma (1); gastric cancer (1); lung squamous cell carcinoma (1); prostate adenocarcinoma (1).